NLRP3 (NLR family pyrin domain containing 3)
Diseases named in the same sentence as NLRP3 in open-access papers (continued):
Sharing a sentence is not in itself a finding about the gene and the disease.
Obesity (continued). "However, inconsistent with the previous findings that NLRP3 rs10754558 was significantly associated with GA, we did not observe significant correlation between the polymorphism and GA/HUA risk, suggesting their potential interaction with environment, such as BMI, obesity, and age." (PMID 36051474, 2022). "In most studies, NLRP3 and caspase-1 KO mice were found to be resistant to HFD-induced obesity and insulin resistance." (PMID 36065376, 2022). "Mechanistically, it has been proposed that lipid messengers (e.g., palmitate and ceramides), which are elevated in both individuals with obesity and HFD-challenged mice, act as signals for NLRP3 inflammasome priming and activation." (PMID 36483560, 2022). "Increases in the levels of ILC3s are observed in adipose and lung tissues in obesity, and ILC3s can mediate the development of AHR in HFD-induced obese mice with NLRP3 and IL-1β." (PMID 36051916, 2022). "Therefore, the present study reports that saroglitazar could ameliorate obesity and associated inflammation through involvement of NLRP3 and NF- κB proteins which has not been demonstrated earlier." (PMID 36033946, 2022). "HFD induced obesity, and an increase in blood lipid level, and levels of P2X7, NLRP3, interleukin-1β, caspase-1, and collagen I in myocardial tissue." (PMID 36320147, 2022). "It is reasonable to assume that obesity promotes the development of DCM via NOX4 participating in the immune response and ferroptosis by activating NADPH oxidase and NLRP3 inflammasomes." (PMID 36547458, 2022). "Preclinical studies have shown that baicalin also exhibits antidepressant effects via GSK3β/NF-κB/NLRP3 signaling and HPA axis normalization, also mitigating obesity and insulin resistance in diabetic patients." (PMID 34112182, 2021). "In eWAT, the increasing activity of the NLRP3 inflammasome leads to increases in MAOA oxidation, thereby dampening lipolysis and promoting obesity." (PMID 35046893, 2021). "In conclusion, NLRP3 inflammasomes are critical for the development and progression of obesity and T2DM, especially IL-1β, a product of NLRP3 inflammasome activation." (PMID 34737754, 2021). "In the development of obesity and T2DM, NLRs can sense hyperglycemia and then elicit NLRP3 inflammasome-mediated inflammation." (PMID 31174550, 2019). "NLRP3 inflammasome participates in immune dysfunction leading to chronic inflammation, insulin resistance, and metabolic disorders in HFD-induced obesity in mice." (PMID 34104129, 2019). "The role of NLRP3-inflammasome in the HFD-induced and obesity-related cardiovascular disease has been poorly studied." (PMID 29245937, 2017). "Moreover, the biochemical analysis showed that obesity increased the caspase-1 activity and IL-1β production in Asm+/+ mice but not in Asm−/− mice, suggesting the essential role of Asm gene in mediating the obesity-induced NLRP3 inflammasome formation and activation in glomeruli of mice." (PMID 26980705, 2016). "Increased expression of Nlrp3 components are correlated with adiposity in DIO, genetic models of obesity (db/db and ob/ob) and obese humans." (PMID 27128935, 2016). "Knockout of the NLRP3 inflammasome (NLRP3−/−, ASC−/−, and caspase-1−/−) significantly protected mice from HFD-induced obesity, increased adiposity, insulin resistance, glucose intolerance, and inflammation." (PMID 26980705, 2016). "Obesity induces inhibitory phosphorylation of SAMHD1, resulting in cytosolic dNTP accumulation, mitochondrial import through SLC25 transporters, uncontrolled mtDNA synthesis and oxidation, and consequent NLRP3 hyperactivation." (PMID 42112341, 2026). "Because gliosis contributes to obesity pathogenesis, it is not surprising that this beneficial effect of NLRP3 inhibition augments the efficacy of GLP‐1RAs, especially because gliosis does not appear to be a key target for the action of the latter drug class." (PMID 40304241, 2025).
Obesity (continued). "In contrast, people with obesity without COVID-19, despite exhibiting some markers of the NLRP3 inflammasome, are more likely to experience necroptosis mediated by caspase-9." (PMID 40004007, 2025). "Future studies should also examine how chronic Gq activation reshapes macrophage phenotype and whether this signaling intersects with other inflammatory pathways, such as the NLRP3 inflammasome or TLR signaling, during obesity." (PMID 41278909, 2025). "In a study on obesity, adipose tissue from obese participants (n = 186) showed significantly higher NLRP3 gene expression compared to non-obese participants (n = 84) (SMD 1.07; 95% CI, 0.27–1.87)." (PMID 40718836, 2025). "Mice with HFD-induced obesity exhibit increased expression of caspase-1, ASC, and NLRP3." (PMID 38681198, 2024). "Our findings suggest that the serum lipid-lowering treatments may alleviate obesity-induced AHR and lung fibrosis through anti-inflammatory responses by inhibition of RAS and NLRP3 inflammasome, and CCK activity." (PMID 38762465, 2024). "Inflammation is a common link between obesity and cardiometabolic diseases, and TNF-α is one of the main adipokines involved in the inflammatory processes that occur in the context of obesity, mediated by NF-κB, JNK, and NLRP3 inflammasomes." (PMID 38399430, 2024). "Nucleotide-binding oligomerization domain 1 (NOD1) or NOD-like Receptor pyrin domain containing 3 (NLRP3) activation promote metabolic inflammation and insulin resistance while NOD2 activation improves insulin sensitivity and glucose homeostasis during obesity." (PMID 41853552, 2024). "Inhibition of NLRP3 inflammasome activation after PTL treatment was previously reported in a TBI rat model, in a lipopolysaccharide (LPS)-induced AD mouse model and in obesity-induced inflammatory response in a mouse model." (PMID 39327568, 2024). "In the context of obesity, the priming signals that drive the expression of NLRP3 and pro-IL1b in the AT are not yet clearly identified." (PMID 37239938, 2023). "Of the obesity studies, nine (n = 270) were included in the meta-analysis, which showed a significantly higher adipose tissue NLRP3 gene expression in obese (n = 186) versus non-obese (n = 84) participants (SMD 1.07; 95% CI, 0.27, 1.87)." (PMID 37446154, 2023). "In obesity, reducing the AMP-activated protein kinase (AMPK) AMPK reactivity leads to the inhibition of mitophagy and accumulation of damaged mitochondria and intracellular mtROS, release of mtDNA, and the NLRP3 inflammasome activation." (PMID 37372020, 2023). "An increase in IL-1β, IL-18, TNF-α, inflammasome NLRP3 activation, astrogliosis, and BBB permeability in the brain areas involved in the control of the intake of food such as the LH and hippocampus are the hallmarks of obesity-induced neuroinflammation." (PMID 36674982, 2023). "A possible explanation for this discrepancy in NLRP3 results between studies could be the type of tissue (VAT or SAT) and/or the variation in the obesity range used in these studies." (PMID 37446154, 2023). "Given the well-known mechanistic links between obesity, IR, and PCOS, it is plausible to hypothesize that the NLRP3 inflammasome may play a similar role in inducing chronic inflammation in the AT of PCOS women." (PMID 37446154, 2023). "Nucleotide-binding and oligomerization domain-like receptor, leucine-rich repeat, and pyrin domain-containing 3 (NLRP3) inflammasome have been proposed to be influenced by omega-3 PUFA in obesity and obesity-related metabolic disorders, such as insulin resistance." (PMID 37374105, 2023). "Therefore, obesity or T2DM models, effective inhibition of NLRP3 inflammasome activation reduces the inflammatory response of β cells, thereby improving insulin sensitivity by inhibiting the production of IL-1β." (PMID 36993972, 2023).
Obesity (continued). "In our model, obesity resulted in a marked elevation in IL-1, a cytokine frequently cited as proarrhythmic, which was prevented by SGK1 inhibition, perhaps through its effects on the NF-κB and NLRP3 axes." (PMID 35998035, 2022). "Moreover, the anti-obesity drug liraglutide, a glucagon-like peptide-1 (GLP-1) receptor agonist, can alleviate airway inflammation by suppressing NLRP3 inflammasome activity." (PMID 36051916, 2022). "The NOD-like receptor protein 3 (NLRP3) inflammasome has recently been demonstrated to detect nonmicrobial danger signals in dysfunctional AT and involved in obesity-related inflammation." (PMID 35432210, 2022). "Development of asthma was shown to be induced by obesity, as mice fed a high-fat diet (HFD) rapidly developed insulin resistance, hepatic steatosis, airway hyperreactivity, and increased expression of NLRP3 and IL-1β in adipose tissue and the lung as compared with lean mice fed chow." (PMID 35806353, 2022). "In addition, activation of NLRP3 inflammasome in AT exacerbated fibrosis, restricted the healthy expansion of adipocytes and increased circulating levels of FFA during obesity." (PMID 35432210, 2022). "Moreover, ablation of the NLRP3 inflammasome lowered the expression of IL-18 and IFN-γ and macrophage-T-cell interactions during obesity." (PMID 36552805, 2022). "Therefore, to mimic obesity condition in vitro, we first pre-treated BMDMs with GC-VLNs, followed by LPS priming and FFA treatment to activate the NLRP3 inflammasome." (PMID 34646372, 2021). "In animal models, inactivation of NLRP3 prevents ageing- and obesity-induced chronic inflammation, glucose intolerance and nonalcoholic fatty liver disease." (PMID 34789781, 2021). "Indeed, the rapid upregulation of NLRP3 protein in early obesity (after 4- week HFD treatment) was followed by a consistent downregulation of NLRP3, IL-18, and CASP1 in late obesity (after 16- week HFD)." (PMID 34805147, 2021). "Genetic ablation of NLRP3 or inhibition of NLRP3 by MCC950 could relieve high-sugar diet (HSD), HFD or high sugar/fat diet induced obesity, cardiomyocyte apoptosis and inflammation, and improve the antioxidant capacity to ameliorate cardiac injury." (PMID 33796528, 2021). "Several studies disclosed that an ablation of NLRP3 or of the inflammasome components ASC and caspase-1 in mice prevented obesity-induced inflammation in fat depots and liver, ameliorated insulin signaling, increased energy expenditure and prevented liver steatosis as well as pancreatic damage." (PMID 33178196, 2020). "NLRP3 inflammasome ablated mice do not show obesity-induced inflammasome activation in both fat depots and liver and present better insulin signaling." (PMID 32012784, 2020). "Furthermore, the ability of visfatin to mediate obesity-induced podocyte injury via NOD-, LRR- and pyrin domain-containing protein 3 (NLRP3)-inflammasome activation has also been shown." (PMID 33182523, 2020). "In spite of the potential role of the NLRP3 inflammasome in metabolic syndrome, activation of this pathway in fat occurs in a late phase of obesity, thus suggesting that NLRP3 inflammasome is actually not a primary etiologic factor in the disease." (PMID 32012784, 2020). "Moreover, ceramides activate NLR family pyrin domain containing 3 (NLRP3) inflammasome and promote secretion of IL-1β and IL-18 in macrophages, aggravating adipose tissue inflammation and glucose intolerance in obesity." (PMID 33584664, 2020). "Moreover, the NLRP3 inflammasome can be activated by metabolic signaling molecules such as glucose, saturated fatty acids (SFA), and uric acid during obesity, leading to the production of IL-1β and cytokines." (PMID 31835423, 2019). "This revealed a clear pattern of concentric remodeling in obese WT mice (RWT > 0.48), but not in Nlrp3−/− and Asc−/− (Pycard−/−) mice, which were protected against these obesity-induced alterations." (PMID 31379826, 2019).
Obesity (continued). "Whereas, NLRP3 and ASC deficiency did not affect the cardiac hypertrophic response to obesity, it was preventive against left ventricle concentric remodeling and impairment of diastolic function." (PMID 31379826, 2019). "Taken together, our results so far show that NLRP3 and ASC deficiency during obesity does not affect the hypertrophic response but prevents obesity-induced LV concentric remodeling and early signs of systolic and diastolic dysfunction." (PMID 31379826, 2019). "Whether obesity has an impact on CRC development by enhancing inflammatory signaling pathways or through a direct mechanism remain largely unclear and the role of NLRP3 in colon cancer is still controversial." (PMID 30619282, 2018). "In unpublished studies, we have also shown that Ron inhibits the NLRP3 inflammasome in cultured microglia, and mice lacking Ron exhibit elevated NLRP3 inflammasome activation in the hippocampus in the context of diet-induced obesity." (PMID 29941796, 2018). "In addition to ILC2, a team conducting experiments in mouse models of HFD concluded that NLRP3, IL-1β, and ILC3 cells facilitated obesity-related asthma by mediating inflammation." (PMID 30050954, 2018). "Given that both the NLRP3 and NLRP1 inflammasome produce mature caspase-1 to cleave IL-18 and IL-1β, how these opposing effects occur, and in which cellular compartments, to drive or limit obesity remain unanswered questions that will be important to resolve." (PMID 29515457, 2018). "We have investigated the role of the NLRP3-inflammasome in mice lacking the NLRP3 gene and exposed to the different diets inducing obesity." (PMID 29245937, 2017). "Previous studies using genetically modified mice lacking NLRP3 inflammasome components showed that activation of the NLRP3 inflammasome is essential for the induction of obesity-induced inflammation and development of insulin resistance." (PMID 29258239, 2017). "Together, these findings indicate that Nlrp3 gene is not required for Western diet-induced AT inflammation, suggesting that other mechanisms, independent of Nlrp3, mediate AT inflammation with obesity." (PMID 27583382, 2016). "Using mouse diet-induced obesity models, targeting various components of the inflammasome, including NLRP3, caspase-1 and ASC was shown to either prevent obesity, and/or to relieve obesity-induced manifestations, in particular whole-body insulin resistance and hepatic steatosis." (PMID 23341960, 2013). "However, we cannot rule out the contribution of NLRP3 inflammasome activation from other cells, such as immune cells, in IEB alterations associated with obesity; therefore, focused experiments are needed to better investigate this aspect." (PMID 39287080, 2025). "However, we cannot rule out the contribution of NLRP3 inflammasome activation from other cells, such as immune cells, in IEB alterations associated with obesity." (PMID 39287080, 2025). "The heightened expression of NLRP3 in obese controls might reflect a greater response to obesity-related inflammation, independent of PCOS." (PMID 41411269, 2025). "Conversely, though individuals with obesity and without COVID-19 exhibit markers of the NLRP3 inflammasome, the main mechanism of cell death is more likely necroptosis, not pyroptosis, mediated by caspase-9, a non-inflammatory form of cell death, non-related to the NLRP3 inflammasome pathway." (PMID 40004007, 2025). "Thus, ovarian canonical and noncanonical leptin signalling control the activity of the NLRP3 inflammasome in the course of obesity in mice." (PMID 38580672, 2024). "This study represents the first exploration of the effects of the HC and LC exercise protocols, with or without the consumption of BBR, on CRP, IL‐1β, NLRP3, and H19 in middle‐aged men with overweight or obesity and prediabetes, which can be considered an advantage." (PMID 39107107, 2024).
Obesity (continued). "LCN2 participated in obesity and its metabolic complications such as T2DM, and cardiovascular diseases, which may relate to the activation of LCN2 signaling (such as TNF-α/NLRP3/LCN2) inducing mitochondrial dysfunction, oxidative stress, insulin resistance, and macrophage activation in adipocytes." (PMID 39609876, 2024). "Consequently, inhibiting RAS activation, NLRP3, and TGF-β1 expression could offer novel therapeutic avenues for managing asthma in patients with both obesity and asthma." (PMID 38762465, 2024). "In addition, inflammageing and subclinical inflammation, particularly in the context of obesity, share mechanisms such as the TLR pathways, NF-κB pathway, NLRP3 inflammasome activation, oxidative stress, mitochondrial dysfunction, immune cell population alterations, and gut microbiome changes." (PMID 38276294, 2023). "However, the precise mechanism by which obesity activates NLRP3 inflammasome‐mediated pyroptosis in cardiomyocytes is not well characterized." (PMID 37904706, 2023). "Moreover, aerobic exercise could ameliorate obesity-induced inflammation and vascular dysfunction by suppressing NLR family pyrin domain containing 3 (NLRP3) inflammasome, concomitantly reducing the levels of caspase-1 and IL-1β." (PMID 37859981, 2023). "How obesity stimulates ILC2s is not yet clear, but it may also involve NLRP3 inflammasome-derived IL-1β since this cytokine is upregulated in obesity and was recently shown to promote the type-2 cytokine production of ILC2s." (PMID 36466877, 2022). "However, no data on CaSR mediated NLRP3 inflammasome activation of macrophages in obesity has been published." (PMID 35931812, 2022). "The production of inflammatory cytokines during obesity has been well demonstrated to be regulated by the signaling pathway of inhibitor of κB kinase-β (IKK-β) and nuclear factor-κB (NF-κB), c-Jun N-terminal kinase (JNK), and the NLR family pyrin domain containing 3 (NLRP3) inflammasome." (PMID 35563728, 2022). "However, some studies suggest that obesity-mediated inflammation and expression of adipose tissue inflammatory markers is independent of NLRP3 inflammasome activation." (PMID 33435142, 2021). "Adiposity and insulin sensitivity could be regulated by the NLRP3 inflammasome during obesity, demonstrating improved glucose homeostasis in mice lacking Nlrp3 under HFD." (PMID 34459122, 2021). "Additionally, knockouts of NLRP3, ASC, or caspase-1 protect mice from diet-induced obesity." (PMID 34202842, 2021). "Some findings, however, report that obesity-mediated inflammation and the production of proinflammatory cytokines in adipose tissue and NLRP3 inflammasome activation are not interdependent; hence, the findings should further be elucidated in future such studies." (PMID 34362072, 2021). "A recent report shows that, in mice, obesity does not disturb the skeletal muscle calcium handling during contraction, suggesting that this calcium dysregulation could not be involved in NLRP3 activation in skeletal muscle." (PMID 33806797, 2021). "In addition to the MAPK signaling pathway and NLRP3 inflammasome, it is not excluded that OA acts through other downstream pathways to regulate obesity-induced inflammation." (PMID 34393781, 2021). "The authors used a series of dietary obesity and VAT transplantation experiments using Nlrp3−/− mutant mice and Tg mice with inducible deletion of IL1r1 (interleukin 1 receptor type 1) in CX3CR1(CX3C chemokine receptor 1)-expressing cells to verify their hypothesis." (PMID 34070553, 2021). "Furthermore, obesity factors including cholesterol and palmitic acid may interact with AHR signaling through the NLRP3 inflammasome and enhance the activation of markers of atherogenesis." (PMID 33167400, 2020). "However, whereas NLRP3 and ASC deficiency affected body weight during HFD, it did not affect obesity-induced hypertrophic response." (PMID 31379826, 2019).